EMBP1 (embigin pseudogene 1)
Gene: Transcribed unprocessed pseudogene on chromosome 1 (121,519,345 to 121,568,791, forward strand). Ensembl gene ENSG00000231752.
Diseases named in the same sentence as EMBP1 in open-access papers:
EMBP1 is named in the same sentence as 4 diseases in open-access papers, as found by Europe PMC text mining. Sharing a sentence is not in itself a finding about the gene and the disease. The quoted sentences say what the papers report.
breast carcinoma (1 paper, 2014). "The most significant association for follicular lymphoma was with a breast cancer risk variant [rs11249433 in EMBP1: summary OR per allele C = 1.29 (1.08–1.54), p = 0.0095]." (PMID 24598796, 2014).
renal cell carcinoma (1 paper, 2026). "According to bioinformatics analysis, the lncRNA embigin pseudogene 1 (EMBP1) acts as a ceRNA in renal cell cancer via the EMBP1/miR-9-5p/cyclin E2 (CCNE2) axis." (PMID 41431719, 2026). "In accordance with these findings, renal cell cancer tumorigenesis may be promoted by dysregulation of the EMBP1/miR-9-5p/CCNE2 axis." (PMID 41431719, 2026).
cancer (1 paper, 2022). A tumor composed of atypical neoplastic, often pleomorphic cells that invade other tissues. "The ability of HPV integration to alter expression of nearby human genes (within 500 Kb) has been demonstrated in both OPSCC and UCSCC with recurrent integration sites identified near genes implicated in cancer such as MYC, MYB, PVT1, RAD51B, EMBP1, CD274/PD-L1, and SOX2." (PMID 36139648, 2022).
EMBP1 also shares sentences with these, for which no sentence is quoted: follicular lymphoma (1 paper).